SF3B1 (splicing factor 3b subunit 1)
Diseases named in the same sentence as SF3B1 in open-access papers (continued):
Sharing a sentence is not in itself a finding about the gene and the disease.
uveal melanoma (95 papers, 2013 to 2025). A melanoma derived from melanocytes of the uveal tract. "For example, mutations in the splicing factor SF3B1 generate immunogenic neoantigens recognized by CD8+ T cells in at least 20% of SF3B1‐mutated uveal melanoma tumours." (PMID 41416931, 2025). "In uveal melanomas with SF3B1 mutations, these splicing patterns induce the formation of tumor-specific immunogenic neoepitopes." (PMID 38462618, 2024). "Around 10–20% of uveal melanoma cases display mutations in the splicing factor 3B subunit 1 (SF3B1) gene." (PMID 38392052, 2024). "This meta-analysis aimed to evaluate the prognostic significance of driver mutations, including GNAQ, GNA11, BAP1, and SF3B1, in the advancement of uveal melanoma." (PMID 39061150, 2024). "Splicing Factor 3b Subunit 1 (Spliceosome Factor SF3B1) mutations are encountered in 25% of uveal melanomas and present intermediate metastatic risk, with a third of the patients developing metastatic disease at 5 years from the time of diagnosis." (PMID 38732371, 2024). "SF3B1 is the most commonly mutated splicing factor, with approximately 15–20% of mutations occurring in uveal melanoma." (PMID 38462618, 2024). "Mutation of the SF3B1 splice factor in uveal melanoma induces aberrant splicing of hundreds of genes." (PMID 39390592, 2024). "SF3B1 mutations are found in solid tumors such as BC, pancreatic carcinoma, uveal melanoma, and endometrial cancers." (PMID 38003265, 2023). "Approximately 10–20% of uveal melanoma (UM) cases exhibit mutations in the splicing factor 3B subunit 1 (SF3B1) gene." (PMID 37628989, 2023). "Our findings provide a functional explanation for the observed mutual exclusivity of BAP1 and SF3B1 mutations in uveal melanoma." (PMID 34706158, 2022). "Mutations in SF3B1 have been identified at a relatively high frequency in some tumors, such as hematologic malignancies, uveal melanoma (UM), and breast cancers (BC)." (PMID 35562651, 2022). "Although SF3B1 mutations occur in about 20% of uveal melanomas, the here used SK-MEL-239 cell line is SF3B1 wild-type." (PMID 35883549, 2022). "This study describes clinical and genetic characteristics of the largest aggregated cohort of Splicing Factor 3 Subunit B1 (SF3B1)-mutated Uveal Melanoma (UM) in the literature (n = 146)." (PMID 35159112, 2022). "SF3B1 (splicing factor 3 subunit B1) mutation has been reported to be associated with good prognosis as well as late metastases in different series of uveal melanomas." (PMID 34571863, 2021). "In uveal melanoma, SF3B1 mutations are associated with low‐grade disease and a favorable prognosis, whereas their role in mucosal melanoma is not clear to date." (PMID 33724703, 2021). "; one of our splicing factor candidates was SF3B1, a commonly mutated gene in uveal melanoma and CLL and a potential target for cancer treatment." (PMID 33648524, 2021). "Abnormal recognition of the 3′ ss has been confirmed in breast cancer and uveal melanoma with mutations in SF3B1." (PMID 33923658, 2021). "Among our candidates was SF3B1, a splicing factor known to be a driver gene in breast cancer and often mutated in uveal melanoma and chronic lymphocytic leukemia (CLL)." (PMID 33648524, 2021). "Loss of function mutations in BAP1, gain of function mutations in related EIF1AX and SF3B1, and chromosomal 8q gains have been identified as secondary driver mutations in uveal melanomas and are present in a subset of malignant blue nevi." (PMID 35008286, 2021). "In uveal melanoma, SF3B1 mutations are associated with a better prognosis, whereas in other mucosal melanomas, SF3B1 mutations are correlated with a worse prognosis." (PMID 34102999, 2021). "sequenced SF3B1 mutations in 117/105 uveal melanoma patients, respectively, and found that the SF3B1 mutations were all associated with a lower stage and a better prognosis." (PMID 33932092, 2021).
uveal melanoma (continued). "The sample size of this study is too small to reliably investigate the role of BAP1 alternation and SF3B1 mutations in survival of metastatic uveal melanoma patients and this remains to be investigated in future studies." (PMID 34830903, 2021). "R625 mutations in SF3B1 have been described in uveal melanoma, vulvovaginal mucosal melanoma, and other cancers." (PMID 32427851, 2020). "SF3B1 mutations are characterized by disomy 3 and noted to be a marker of good prognosis for uveal melanoma and found in younger patients." (PMID 32429485, 2020). "Some solid tumors, including uveal melanoma, breast cancer, and pancreatic cancer, have relatively low frequencies of SF3B1 mutations compared with hematological malignancies." (PMID 30719229, 2019). "In uveal melanoma, SF3B1 mutations are associated with alternative splicing and indicate a good prognosis." (PMID 30719229, 2019). "Mutations within exons 12–15 of SF3B1, encoding the C-terminal portion of the protein, have been described in 20% of uveal melanoma, 19% of CLL and 1.8% of breast cancers." (PMID 30847022, 2019). "Among the different subtypes of melanoma, deleterious somatic variants in SF3B1 were identified in 20% of uveal melanomas." (PMID 30847022, 2019). "Mutation at codon 625 of the splicing factor 3b subunit 1 (SF3B1) gene (chromosome 2q) is associated with uveal melanoma development." (PMID 31109147, 2019). "A recent study showed that the expression of the oncogene PRAME in a group of uveal melanoma patients allowed the identification of a group of class 1 patients with intermediate metastatic risk, and these uveal melanomas often harbor SF3B1 mutations." (PMID 29156643, 2017). "In this context, it is of interest to note that some mucosal melanomas exhibited mutated genes such as GNAQ and SF3B1, previously observed in uveal melanoma." (PMID 29156643, 2017). "The findings concerning the SF3B1 gene were independently confirmed in another study showing that mutations of this gene are observed in low-grade uveal melanomas associated with good prognosis." (PMID 29156643, 2017). "Mutations in the splicing factors U2AF35, ZRSR2, SRSF2, and SF3B1 are associated with myelodysplastic disorders, chronic lymphocytic leukemia, and solid tumors, including uveal melanoma, with SF3B1 being the most frequently mutated spliceosome component." (PMID 29235465, 2017). "SF3B1 hot spot mutations in uveal melanoma are associated with deregulation of a subset of splice junctions, caused by the use of alternative 3’ss (AG’) upstream of the canonical 3’ss (AG)." (PMID 29156643, 2017). "Mutations in splicing factor 3B subunit 1 gene (SF3B1) have frequently been identified in uveal melanoma, chronic lymphocytic leukemia, and myelodysplasia." (PMID 27564110, 2016). "Our finding that an SF3B1 or EIF1AX mutation is present in a substantial subset of primary LMNs underscores that these tumors genetically resemble uveal melanoma and are different from cutaneous melanoma at the genetic level." (PMID 26769193, 2016). "EIF1AX has recently been reported as recurrently mutated in uveal melanomas, in mutual exclusion with mutations in SF3B1." (PMID 26506417, 2015). "Whilst in patients with CLL these mutations are associated with a poor outcome, in patients with uveal melanoma, SF3B1 mutations are reported to be associated with a good prognosis." (PMID 25424858, 2015). "Codon 625 of the SF3B1 gene, encoding splicing factor 3B subunit 1, is consistently mutated in low-grade uveal melanomas with good prognosis." (PMID 24743024, 2014). "In addition, SF3B1 somatic mutations are present in a range of solid tumors, with high frequency (around 20%) in uveal melanoma and more rarely in cases of breast cancers or cutaneous melanomas for example." (PMID 38517966, 2024). "Notably, we found that SF3B1 mutations as recurrent genetic events in MM were more common in esophageal and uveal melanomas, which is similar to that reported in recent studies." (PMID 37649078, 2023).
uveal melanoma (continued). "The metastatic risk of uveal melanoma (UM) is defined by a limited number of molecular lesions, somatic mutations (SF3B1 and BAP1), and copy number alterations (CNA): monosomy of chromosome 3 (M3), chr8q gain (8q), chr6p gain (6p), yet the sequence of events is not clear." (PMID 37958591, 2023). "Additionally, higher percentages of GNAQ and GNA11 mutations were observed in patients with uveal melanoma, and a higher percentage of SF3B1 mutations in patients with esophageal and uveal melanoma." (PMID 37649078, 2023). "Indeed, mutation of the splicing factor SF3B1 has been shown to induce tumor-specific ASE-derived neoepitopes that are recognized by CD8 T cells from uveal melanoma patients." (PMID 36077528, 2022). "Moreover, SF3B1 mutations have also been identified in many solid tumor types including uveal melanoma, breast, pancreatic, and prostate cancer." (PMID 35027467, 2022). "Moreover, the impact of SF3B1 mutations on overall survival is disease dependent, for example, SF3B1 mutations in uveal melanoma are associated with improved overall survival, while associated with poor overall survival in acute myeloid leukemia." (PMID 35027467, 2022). "Furthermore, we found mutual exclusivity of SF3B1 or BAP1 driver mutations in all patients with uveal melanoma." (PMID 32825510, 2020). "Patients with uveal melanoma who harbor SF3B1 mutations are reported to have better prognoses." (PMID 29383138, 2017). "SF3B1 mutations are associated with a good prognosis for uveal melanoma." (PMID 27043545, 2016). "However, it was shown that patients with disomy 3 tumors and SF3B1 mutations have increased risk of metastatic disease at a longer follow-up time (Koopmans AE, Prognostic implications of acquired genetic changes in uveal melanoma." (PMID 27800275, 2016). "Mutations in the splicing factor SF3B1 are found in uveal melanoma." (PMID 26842708, 2016). "Hotspot mutations in the spliceosome gene SF3B1 are reported in ∼20% of uveal melanomas." (PMID 26842708, 2016). "Finally, the U2-dependent spliceosome proteins, SF3B1, U2AF35, U2AF65, and PRRF40B, are significantly mutated in solid tumors of lung adenocarcinomas, while mutations in SF3B1 have been associated with breast cancer, uveal melanoma, and PC." (PMID 26498691, 2015). "Given the previous association of SF3B1 mutations with differential splicing in uveal melanoma, we hypothesised that SF3B1 K700E mutations in breast cancer would also lead to differential splicing." (PMID 25424858, 2015). "Hotspot mutations in SF3B1 were recently reported in uveal melanoma." (PMID 23694694, 2013). "More recently, studies have identified mutations in SF3B1 in subsets of solid tumours from multiple anatomic sites (see ref 11 for a recent review), including 15% of chronic lymphocytic leukaemias (CLLs), 9.7% of uveal melanomas, 4% of pancreatic cancers, and 1.8% of breast cancers." (PMID 25424858, 2015). "The first mutation set encompasses the eight UM driver genes according to the TCGA study, divided into “uveal melanoma initiating mutations” (CYSLTR2, GNA11, GNAQ and PLCB4) and “second hit mutations with prognostic impact” (BAP1, EIF1AX, SF3B1 and SRSF2)." (PMID 39858540, 2025). "Hotspot heterozygous point mutations in SF3B1 are the most common across cancer types including CLL, MDS, and uveal melanoma." (PMID 39303038, 2024). "Uveal melanoma-related genes (BAP1, SF3B1, GNAQ/11) can also be mutated in CMs, albeit infrequently." (PMID 37761808, 2023). "Overall, we provide evidence of the oncogenic involvement of mutant SF3B1 in uveal melanoma through a metabolic switch to glycolysis, revealing vulnerability to glycolysis inhibitors as a promising therapeutic strategy." (PMID 35565242, 2022). "Mutations in SF3B1 have also been found in CLL, acute myeloid leukemia, uveal melanoma, and breast cancer." (PMID 33923658, 2021).
uveal melanoma (continued). "Typical uveal melanoma-related mutations were found in seven cases (15%): one case with GNAQ p.R183Q, one with GNA11 p.R183C, two with SF3B1 p.R625C/H, and three with BAP1 missense/nonsense supposedly somatic mutations." (PMID 34359736, 2021). "Based on our molecular findings, CM comprises a separate entity within melanoma, although there are overlapping molecular features with uveal melanoma, such as the presence of BAP1 and SF3B1 mutations." (PMID 34071371, 2021). "SF3B1 mutations are also found in chronic lymphoid leukemia (CLL), where they are associated with poor outcome, in uveal melanoma (20%) and to a lesser extent in breast and pancreatic cancers." (PMID 32168916, 2020). "In uveal melanoma, GNAQ and GNA11 gene mutations are frequently found and prognosis is based on mutation status of BAP1, SF3B1 and EIF1AX genes." (PMID 33396957, 2020). "Uveal melanoma has been thought to result from an initiating GNAQ/GNA11 mutation, followed by a secondary BSE event from mutations in the genes BAP1, SF3B1, and EIF1AX." (PMID 32429485, 2020). "Tumors of uveal melanoma (UM) patients with somatic BAP1, SF3B1, or EIF1AX mutations show a distinct chromosomal copy number variation (CNV) pattern." (PMID 31426461, 2019). "Uveal melanomas, in contrast to conjunctival melanomas, lack BRAF or NRAS mutations but frequently have mutations in GNAQ, GNA11, BAP1, SF3B1 or EIF1AX." (PMID 28938534, 2017). "Studies have highlighted that primary tumours with SF3B1 mutations display alternative splicing in selected key genes in CLL, MDS, and uveal melanoma, and that this signature is conserved between cancer sites and is independent of the mutant amino acid." (PMID 25424858, 2015). "Both cases lacked mutations in the common uveal melanoma tumor suppressors, SF3B1, BAP1, and EIF1AX." (PMID 39804140, 2025). "In addition, the presence of uveal melanoma-related hotspot mutations (including BAP1, SF3B1, and GNAQ/11) in CM has been linked to advanced disease and increased risk for metastasis and death." (PMID 40521590, 2025). "In our cohort of primary uveal melanomas from vfDNA+/UM+ patients, BAP1 alterations occurred throughout the entire gene, most of the SF3B1 mutations affected position p.R625, and EIF1AX mutations were found at various positions within the first two exons of the gene." (PMID 40240901, 2025). "On the other hand, 20–25% of cases of uveal melanoma result from genetic changes in the SF3B1 gene." (PMID 38540335, 2024). "The progression of uveal melanoma relies on a second genetic driver event, such as the inactivation of BAP1 (about 60% of cases) on chromosome 3p21, mutation in the Splicing Factor 3b Subunit 1 (Spliceosome Factor SF3B1) (about 25% of cases), or EIF1AX mutation (about 15–17% of cases)." (PMID 38732371, 2024). "A total of 99 of these 118 patients (84%) had detectable ctDNA at baseline and on treatment, of whom 94 had mutations detected in one or more uveal melanoma genes (GNAQ, GNA11, SF3B1, PLCB4, CYSLTR2) at a variant allelic frequency of >0.3 at baseline and were included in the analyses." (PMID 36229663, 2022). "We also detected splice outliers common to uveal melanoma regardless of SF3B1 mutation status, and these results showed strong concordance in an independent melanoma cohort." (PMID 34031440, 2021). "Furthermore, the U2 snRNP has received a lot of attention due to a number of mutations in its protein member splicing factor 3B subunit 1 (SF3B1) in chronic lymphocytic leukemia and uveal melanoma." (PMID 33668200, 2021). "SF3B1 mutations are present in approximately 25% of malignant blue nevi and 15% of uveal melanomas while EIF1AX mutations are present in approximately 8% of malignant blue nevi and 24% of uveal melanomas." (PMID 35008286, 2021).
uveal melanoma (continued). "It has been discovered that BRD9, PPP2R5A, and DVL2, are candidate genes for alternative splicing in SF3B1 K700-mutant chronic lymphocytic leukemia, while ABCC5, UQCC, and CRNDE are possible targets in three uveal melanoma cases mixed with R625 and K700 mutations." (PMID 34350118, 2021). "Uveal melanoma (UM) has well-characterised somatic copy number alterations (SCNA) in chromosomes 1, 3, 6 and 8, in addition to mutations in GNAQ, GNA11, CYSLTR2, PLCB4, BAP1, SF3B1 and EIF1AX, most being linked to metastatic-risk." (PMID 32340176, 2020). "Moreover, analysing uveal melanoma drivers of mutations, PRAME+ status was found to be directly associated with SF3B1 alterations, while it was inversely associated with EIF1AX changes in class 1 tumours." (PMID 31109147, 2019). "The impact of SF3B1 mutations on patient outcomes varies according to tumor type; for instance, it is associated with poor outcomes in CLL patients but with good prognoses in uveal melanoma patients." (PMID 29383138, 2017). "Finally, SF3B1 and EIF1AX mutations have been reported in primary leptomeningeal melanocytic neoplasms, thus suggesting a similarity between these tumors and uveal melanomas." (PMID 29156643, 2017). "We conclude that recurrent mutations in codon 625 of SF3B1 as reported in uveal melanoma are not present in most types of cutaneous melanoma." (PMID 23694694, 2013). "Our current study would signify that SF3B1 mutations, occurring in almost 20% of uveal melanoma, do not play a major role in cutaneous melanoma." (PMID 23694694, 2013). "None of the remaining 81 samples showed a mutation in SF3B1 as seen in a control sample from a uveal melanoma." (PMID 23694694, 2013). "Also at pre-clinical stage, PRT543 on Splicing factor 3b subunit 1 (SF3B1) uveal melanoma MEL202 (SF3B1R625G active mutant) and MEL270 (SF3B1WT) cell lines showed downregulation of SF3B1 target genes associated with increased intron retention, predominantly in the MEL202 mutant." (PMID 39703687, 2024). "However, codon R625 repeat mutations in SF3B1 in uveal melanomas are absent in most cutaneous melanomas." (PMID 38462618, 2024). "Most of the mutations in SF3B1 are clustered near the HEAT repeat domains 4 to 7 (HR4–HR7), with the most frequently mutated residues being K700 and K666 in MDS and CLL; while mutations in the R625 position are the most commonly occurring allele in uveal melanoma." (PMID 37510283, 2023). "Interestingly, similar SF3B1 mutations are found in a subset of uveal melanomas, another non-UV related melanoma subtype, which is genetically characterized by constitutive activation of the Gαq signaling pathway." (PMID 35706047, 2022). "In addition to observing splice events associated with SF3B1 mutation, we also observed splice events common across the TCGA uveal melanoma cohort, irrespective of SF3B1 mutation status." (PMID 34031440, 2021). "This suggests that the R625 missense SF3B1 mutations and SRSF2 mutations in UM are different compared to the spliceosome gene mutations in hematological cancers, and probably target a different, as yet unknown, set of genes involved in uveal melanoma etiology." (PMID 31426461, 2019). "According to these findings, it was proposed that SF3B1 mutations help to define a subgroup of uveal melanomas associated with metastatic risk that is intermediate between uveal melanomas with BAP1 mutations (high risk) and uveal melanomas with EIF1AX mutations (low risk)." (PMID 29156643, 2017). "In addition to hematological malignancies, lower frequencies of SF3B1 mutation are also found in solid tumors such as breast cancers (1.8%), pancreatic carcinoma (4%), uveal melanoma (9.7%), and endometrial cancers (percentages not reported)." (PMID 29383138, 2017). "However, it is currently unknown whether these LMNs harbor mutations in BAP1, SF3B1 and/or EIF1AX like uveal melanomas as well." (PMID 26769193, 2016).